ANXA5 (annexin A5)
Diseases named in the same sentence as ANXA5 in open-access papers (continued):
Sharing a sentence is not in itself a finding about the gene and the disease.
myocardial infarction (20 papers, 2008 to 2023). Gross necrosis of the myocardium, as a result of interruption of the blood supply to the area, as in coronary thrombosis. "The NM_001154.4:c.-1C > T transition in the ANXA5 gene slightly increases the risk of myocardial infarction in men." (PMID 37344844, 2023). "Annexin A5 has been used to label apoptotic cell death for diagnostic imaging in patients with cancer and acute myocardial infarction because of its ability to bind to the externalized phosphatidylserine, a characteristic feature of apoptosis." (PMID 38269269, 2023). "Studies in patients with cardiovascular disease have shown that intracardiac uptake of Annexin A5 can be caused by myocardial infarction, ongoing heart failure, intracardiac tumor and/or an infection." (PMID 24216991, 2013). "Treatment with exogenous ANXA5 reveals that labeled ANXA5 accumulates in a punctate pattern in the infarcted area, which is significantly reduced in the infarcted area of myocardial infarction after 3 weeks." (PMID 37405052, 2023). "Myocardial infarction leads to elevated levels of endogenous ANXA5, which is a self-protective mechanism of the body." (PMID 37405052, 2023). "On the other hand, our results showed an increase in the expression of ANXA5, similar to that in human patients with myocardial infarction in which cell death in the infarct area was marked by annexin-V after reperfusion." (PMID 36979032, 2023). "For example, plasma Annexin A5 has previously been shown to be elevated in patient with acute myocardial infarction and is acutely increased after angioplasty induced AMI." (PMID 28642677, 2017). "Preclinical and clinical data of 99mTc-HYNIC-Annexin A5 imaging in myocardial infarction support this." (PMID 24216991, 2013). "Increased plasma AnxA5 has been reported in patients with myocardial infarction and unstable angina." (PMID 23284897, 2012). "Interestingly, the use of Anxa5 as a clinical tool for visualization of cell death has been suggested to be important in monitoring pathologies such as atherosclerosis, myocardial infarction, and cancer." (PMID 26022216, 2015). "Accordingly, the present study was aimed to (a) construct a bifunctional SDF‐1‐AnxA5 fusion protein, (b) verify whether the bispecific fusion protein has the biological functions of both native SDF‐1 and AnxA5 (c) and test the protective effect of SDF‐1‐AnxA5 after mouse myocardial infarction." (PMID 31468674, 2019).
viral infection (20 papers, 2011 to 2025). "To analyze the role of the interacting proteins during viral infection, we examined previously published proteomic databases and found that EEF2, ANXA1, ANXA5, SLADRA, CLTA, and FTH1 were significantly enriched and FTH1 was notably upregulated in ASFV-infected PAMs." (PMID 40661982, 2025).
COVID-19 (18 papers, 2020 to 2025). A disease caused by infection with severe acute respiratory syndrome coronavirus 2. "This clinical trial aimed to evaluate the pharmacokinetic (PK) properties of the recombinant human annexin A5 (SY-005) in severe COVID-19." (PMID 38269269, 2023). "Since severe COVID-19 is a manifestation of sepsis and involves these pro-inflammatory and coagulation pathways, annexin A5 is a viable treatment candidate." (PMID 38269269, 2023). "Severe COVID-19 can be complicated by coagulopathy, and annexin A5 has been shown to have a moderate anticoagulant effect." (PMID 38269269, 2023). "In the current study, a correlation of ANXA5 with the SARS-CoV-2 exposure of COVID-19 patients was found (rp = 0.677; p = 0.002; n = 18)." (PMID 34859078, 2021). "We have started a randomized, double blind and placebo-controlled phase 2 clinical trial to evaluate safety, tolerance and pharmacokinetics of recombinant human annexin A5 in COVID-19 patients with sepsis (NCT04748757)." (PMID 34566657, 2021). "ANXA5 has also been identified as an autoantigen of the antiphospholipid syndrome, which is common in COVID-19 patients." (PMID 34859078, 2021). "Safety and efficacy of recombinant human annexin A5 are currently being studied in clinical trials in sepsis and severe COVID-19 patients." (PMID 34566657, 2021). "Depending on COVID-19 disease status and mortality, increased amounts of annexin A5 (ANXA5), eukaryotic initiation factor 4A-I (EIF4A1), and transaldolase (TALDO1) were found in the platelet proteome and also correlated with the nasopharyngeal viral load." (PMID 34859078, 2021). "ANXA5, the major annexin in human platelets, was significantly increased in COVID-19 patients compared to healthy controls (FC = 1.26; p = 0.007)." (PMID 34859078, 2021). "Nevertheless, the platelet protein alterations detected in the current study, such as the increased concentration of ANXA5, seem important for the pathology of COVID-19 and should therefore be made available to the public as soon as possible." (PMID 34859078, 2021). "Overall these observations implicate, that the COVID-19-related increased levels of ANXA5 in platelets may also lead to increased concentrations of anti-ANXA5 antibodies and thus to COVID-19-related APS." (PMID 34859078, 2021). "Notably, the presented results on elevated platelet ANXA5 levels in fatal COVID-19 courses should also be relevant to an ongoing study (NCT04748757), in which patients with severe COVID-19 courses are infused with recombinant ANXA5 to counteract inflammation and thrombosis." (PMID 34859078, 2021). "However, the significant changes regarding increased levels of ANXA5, EIF4A1 and TALDO1 are so far unique for the platelet proteome of COVID-19 patients." (PMID 34859078, 2021). "Another change in platelet proteome that may be highly relevant for the pathogenesis of COVID-19 is the increasing amount of ANXA5 in the platelets of COVID-19 patients, which was significantly higher in non-survivors." (PMID 34859078, 2021). "ECM-associated proteins include several anticoagulant proteins (e.g. the annexin family members ANXA3, ANXA4, ANXA5, and ANXA8L1) of ECM-affiliated proteins were markedly diminished, which is consistent with the results indicating coagulation dysfunction in the COVID-19 patients." (PMID 33060566, 2020).
Sepsis (18 papers, 2012 to 2025). Sepsis is defined as life-threatening organ dysfunction caused by a dysregulated host response to infection. "We and others have shown that recombinant human annexin A5 (Anx5) treatment inhibits pro-inflammatory cytokine production and improves survival in rodent sepsis models." (PMID 37375784, 2023). "Preclinical studies have shown that annexin A5 inhibits pro-inflammatory responses and improves organ function and survival in rodent models of sepsis." (PMID 38269269, 2023). "The protective effects of annexin A5 in the sepsis models are mediated in part by inhibiting LPS and high-mobility group box-1 (HMGB1) binding to the TLR4/MD2 complex." (PMID 38269269, 2023). "In mice infected with E. coli, annexin A5 treatment decreases circulating EVs and dose-dependently delays the development of sepsis." (PMID 34566657, 2021). "Annexin A5 also reduced thrombin generation induced by cecal ligation and perforation, which is a clinically relevant model of sepsis." (PMID 34566657, 2021). "AD-EVs also showed less Anxa5, an anticoagulant protein that has a protective effect on sepsis coagulopathy, and activated ATP-related pathways, which may be associated with the production of massive reactive oxygen species and proinflammatory pathways." (PMID 37175936, 2023). "In addition, it was demonstrated that BM-EVs have more Anxa5, an anticoagulant factor that protects against multiple organ dysfunction in sepsis." (PMID 37175936, 2023). "Since annexin A5 inhibits HMGB-1 interaction with TLR4 in models of sepsis and inflammation, it could interfere with HMGB1-mediated SARS-CoV-2 infection." (PMID 34566657, 2021).
atherosclerosis (16 papers, 2011 to 2025). A disease characterized by the build-up of fatty material and calcium deposition in the arterial wall resulting in partial or complete occlusion of the arterial lumen. "99mTC radiolabeled AnxA5 and AnxA5-conjugated gold nanoparticles were valuable diagnostic imaging tools in mouse models for atherosclerosis." (PMID 33810523, 2021). "In genetically predicted levels, higher expression of ANXA5, CCDC71L, MED8, MRAS, MRPS6, NTAN1, and SLA5A3 was positively associated with atherosclerosis risk." (PMID 39766313, 2024). "However, none of these two parameters was independently associated with endothelial dysfunction and subclinical atherosclerosis, suggesting that circulating sF11R and ANXA5 might have a minor impact on the pathophysiology of atherosclerosis in diabetic patients." (PMID 36009365, 2022). "The soluble human F11 receptor (sF11R) and annexin A5 (ANXA5) play crucial roles in inflammatory thrombosis and atherosclerosis." (PMID 36009365, 2022). "The ability of AnxA5 to bind cell surface PS on apoptotic cells has proven valuable for the diagnosis of atherosclerosis." (PMID 33810523, 2021). "Our group has demonstrated that AnxA5 reduces inflammation in advanced atherosclerosis and contributes to stabilization of the advanced plaques in the ApoE-/- mouse model of atherosclerosis." (PMID 29267398, 2017). "This study shows, that the administration of AnxA5 in the setting of early, onset atherosclerosis is protective and reduces atherosclerotic development as well as stabilizing the plaque." (PMID 29267398, 2017). "We now investigated the effects of AnxA5 administration on the onset of atherosclerosis development." (PMID 29267398, 2017). "In conclusion, treatment with AnxA5 before the onset of atherosclerosis reduces plaque formation in a murine model of atherosclerosis in part by reducing apoptotic rates further to its beneficial effect on macrophage infiltration and activation." (PMID 29267398, 2017). "In conclusion, the treatment with AnxA5 in the early stages of atherosclerosis reduces plaque formation in a murine model of atherosclerosis in part by reducing apoptotic rates further to its beneficial effect on macrophage infiltration and activation." (PMID 29267398, 2017). "As a biochemical marker of atherosclerosis, the concentration of ANXA5 serves as a standard for clinical diagnosis of cardiovascular complications in kidney disease." (PMID 27878450, 2017). "We extend the current knowledge by demonstrating that a short-term treatment of AnxA5 inhibits plaque inflammation in a murine model of advanced atherosclerosis." (PMID 25214012, 2014). "Future studies are needed to determine if AnxA5-targeting of exposed PS is a useful strategy to suppress chronic plaque inflammation in patients with advanced atherosclerosis." (PMID 25214012, 2014). "In the present study, we demonstrate that short-term treatment with AnxA5 reduces plaque macrophage content in advanced atherosclerotic lesions in a murine model of atherosclerosis." (PMID 25214012, 2014). "The usefulness of molecular imaging using 18F-FDG and 99mTc-annexin A5 for evaluating the therapeutic effects of irbesartan on atherosclerosis was also suggested." (PMID 24586699, 2014). "In conclusion, short-term treatment of AnxA5 reduces plaque inflammation in a murine model of atherosclerosis through interfering with recruitment and activation of monocytes to the inflamed lesion site." (PMID 25214012, 2014). "In addition, ANXA5 has anticoagulant properties and also inhibits atherosclerosis and improves endothelial function in mouse models." (PMID 35982610, 2023). "Annexin A5 has been proposed as an imaging biomarker of CV risk since preclinical and clinical studies showed that exposure of PS on the cell surface in the CVS is an attractive biological target in atherosclerosis, heart failure, and cardiac ischemia." (PMID 36614132, 2022).
atherosclerosis (continued). "In this study, we hypothesized that changes in circulating sF11R and ANXA5 could influence indices of endothelial dysfunction and subclinical atherosclerosis in patients with poorly-controlled T2DM." (PMID 36009365, 2022). "Furthermore, anxA5 reduced vessel inflammation and atherosclerosis after arterial cuff placement or vein graft surgery." (PMID 34405304, 2021). "We therefore hypothesize, that the anti-apoptotic effect of AnxA5 may be overwhelmed in the later stages of atherosclerosis due to the much higher rates in larger more complex plaques." (PMID 29267398, 2017). "Indeed, our flow chamber results indicate that the administration of AnxA5 can interfere with monocyte recruitment into the cell, a major process for the initiation of atherosclerosis." (PMID 29267398, 2017). "The actions of AnxA5 on atherosclerosis are incompletely understood." (PMID 25214012, 2014). "Thus, we investigated the effect of exogenous AnxA5 on plaque morphology and phenotype of advanced lesions in a murine model of atherosclerosis." (PMID 25214012, 2014). "These technical limitations might have contributed to the inability to detect any apoptotic changes in the aortic arch of apoE−/− mice treated with low dose radiation, which is considered to protect against atherosclerosis, when using 99mTC-labeled AnxA5 for autoradiographic analysis." (PMID 33810523, 2021). "Taken together, treatment with AnxA5 might be a promising option to modulate vascular inflammation to reduce atherosclerotic lesion progression and plaque vulnerability in patients with advanced atherosclerosis." (PMID 25214012, 2014). "As we expected, the present results indicate that the therapeutic effects of irbesartan on atherosclerosis can be quantitatively evaluated using 14C-FDG and 99mTc-annexin A5." (PMID 24586699, 2014). "There was no change in carotid artery atherosclerosis between AnxA5 (0.175 ± 0.026 mm3) and vehicle treated mice (0.175 ± 0.042 mm3, P = ns)." (PMID 25214012, 2014). "Thus, remissions of inflammation and apoptosis as potential therapeutic effects of irbesartan on atherosclerosis were observed by histochemical examination and molecular imaging using 14C-FDG and 99mTc-annexin A5." (PMID 24586699, 2014).
antiphospholipid syndrome (15 papers, 2013 to 2026). A disorder caused by the presence of autoantibodies directed against phospholipids, causing a hypercoaguable state, which may result in blood clots, stroke, heart attack, and in women, significant pregnancy-related complications, including miscarriage and still birth. "Antiphospholipid antibodies displace the AnxA5 protective shield and this was linked to pro-thrombotic events in antiphospholipid syndrome patients leading to pregnancy complications." (PMID 38383560, 2024). "Annexin A5 (ANXA5) is an anti-apoptotic protein involved in the modulation of immune response repeatedly implicated in autoimmune diseases such as antiphospholipid syndrome, rheumatoid arthritis, lupus, type-1 diabetes, and autoimmune myocharditis." (PMID 26717306, 2015). "Nevertheless, AnxA5-based approaches could become a suitable tool to overcome poor obstetric outcomes caused by antiphospholipid syndrome, preeclampsia and SLE in humans." (PMID 33810523, 2021). "Annexin A5 resistance is regarded as one of the antiphospholipid syndrome’s pathogenesis mechanisms." (PMID 40242764, 2025). "In this regard, antibody-mediated inhibition of the anticoagulant property of annexin A5 has been proposed to occur in recurrent pregnancy losses observed in patients with lupus erythematosus and antiphospholipid syndrome." (PMID 23358253, 2013). "Annexin A5 (ANXA5) serves as an anticoagulant phospholipid "shield," which can be compromised by antiphospholipid antibodies (aPLs), contributing to thrombosis and obstetric complications in antiphospholipid syndrome (APS) and increasing vascular risk in SLE." (PMID 41542857, 2026). "Thus, in patients with antiphospholipid syndrome it has been observed that the presence of anti-annexin A5 antibodies promotes placental thrombosis." (PMID 23358253, 2013). "Finally, in patients with anti-phospholipid syndrome (APS), circulating aPL (anti-phospholipid) antibodies disrupt the anticoagulant crystallization shied of anxA5 and consequently highly promote thrombosis in the placenta and the cardiovascular system." (PMID 34405304, 2021).
Stroke (15 papers, 2012 to 2025). Sudden impairment of blood flow to a part of the brain due to occlusion or rupture of an artery to the brain. "99mTc-labeled annexin A5 has been shown to have higher uptake in the carotid arteries of vulnerable stroke patients.16899mTc-tagged annexin A5 specifically accumulates in vascular atherosclerotic lesions, which is a great advantage." (PMID 29196910, 2018). "In humans, Technetium-99 m labelled annexin A5 has been featured in over 20 clinical trials, including monitoring tumor apoptosis in response to therapy, stroke severity and prosthetic joint infection." (PMID 29673196, 2018).
diabetes (14 papers, 2011 to 2025). "The clinical significance of sF11R/ANXA5 association in diabetes warrants further investigation in a larger population." (PMID 36009365, 2022). "In summary, it is conceivable that the complexity of diabetes physiopathology might directly or indirectly result in interactions between circulating sF11R and ANXA5 and other diabetes-risk factors, such inflammation, which requires further investigation." (PMID 36009365, 2022). "Collectively, our data suggest that ceramide-mediated ICMR in vascular endothelial cells is impaired during diabetes mellitus due to dissociation of ceramide with annexin A5 and ASM play a critical role in this ICMR." (PMID 35874544, 2022). "Antibodies against ANXA5 have been shown to interfere with ANXA5 functions, leading to thrombotic complications during diabetes." (PMID 36009365, 2022). "Since targeting of annexin A5 after forearm IR was low in patients with diabetes, the potential window of protection by ischemic preconditioning was smaller." (PMID 23051145, 2012). "The diabetes-induced increases in Dbi and Anxa5 protein and mRNA expression were completely normalized." (PMID 21249158, 2011). "Annexin A5, used as a probe to detect apoptosis, was highly abundant in the diabetes group." (PMID 35454982, 2022). "Although much attention has been focused on the atherothrombotic state in diabetes, our study clearly documents a positive association between circulating sF11R and ANXA5 in poorly-controlled diabetic patients, but not in well-controlled patients." (PMID 36009365, 2022). "We are aware of differences in race that could account for discrepancies among studies; therefore, this may limit our ability to extend this investigation to a more rigorous analysis of the role of sF11R/ANXA5 in diabetes." (PMID 36009365, 2022). "Consistently, the association of ceramide with annexin A5 was significantly reduced in the coronary arterial endothelium of mice with streptozotocin-induced diabetes mellitus compared to that in non-diabetic control mice." (PMID 35874544, 2022). "To examine the effects of hyperglycemia on the association between ceramide level and annexin A5 expression in the coronary endothelium, we analyze the co-localization of ceramide or annexin A5 to endothelial marker vWF in coronary arteries of mice with streptozotocin-induced diabetes." (PMID 35874544, 2022). "Our data further demonstrate that, in mice under either control condition or with streptozotocin-induced diabetes, ASM gene deletion causes a decrease in the co-localization of ceramide with vWF, which correlates well with a concomitant decrease in the co-localization of annexin A5 with vWF." (PMID 35874544, 2022). "It is noteworthy that the lack of associations between sF11R and ANXA5 with vascular outcome could be due to single basal determination of these two circulating markers, and it remains unclear whether the results would differ substantially with repeated measurements during diabetes." (PMID 36009365, 2022).